EGFR (epidermal growth factor receptor)
Diseases named in the same sentence as EGFR in open-access papers (continued):
Sharing a sentence is not in itself a finding about the gene and the disease.
glioma (continued). "Recently, we have reported that levels of activated nuclear β-catenin are positively correlated with glioma grades and that PFKP plays an instrumental role in EGFR activation-induced β-catenin transactivation in GBM cells." (PMID 36435833, 2022). "C-E-Cad maintains the tumorigenicity of glioma stem cells by binding to the EGFR CR2 domain via a unique 14-amino-cid carboxy terminus, which activates EGFR independently of EGF." (PMID 36506086, 2022). "A reduction in PFKP expression largely reduced EGFR activation-induced VEGF mRNA expression and its protein expression in glioma stem cells (GSCs), LN229, and U251 cells." (PMID 36435833, 2022). "Glioma patients with wild-type IDH1, mutant EGFR or mutant PTEN showed higher expression of SLC11A1 than those with other phenotypes." (PMID 36531992, 2022). "Knockdown of TRIM11 inhibited glioma cell proliferation, migration, and invasion, whereas low levels of TRIM11 resulted in downregulation of EGFR, p-c-Raf, p-MEK1/2, and p-44/42MAPK." (PMID 36139694, 2022). "Here, we found that EGFR was expressed in most of our samples (91.7%) and overexpressed in around 60% of GBM patients, therefore failing to discriminate among glioma grades." (PMID 36400876, 2022). "Of all analyzed MGMT methylated gliomas, 19% showed EGFR amplification, and 22% of MGMT unmethylated gliomas showed an EGFR amplification." (PMID 35453544, 2022). "In glioma cells, the epidermal growth factor (EGF)/EGFR signaling through ERK1/2 leads to the phosphorylation of α-catenin, which, together with cadherin, forms a complex linked to the cytoskeleton, promoting β-catenin transactivation and glioma cell invasion." (PMID 35303162, 2022). "Distinct proteins have been identified in different glioma subtypes, including YKL40, fibronectin 1 (FN1), EGFR, and Stat3." (PMID 35436989, 2022). "Many developmental processes in these cell types are regulated by EGFR-Ras and PTEN-PI3K signaling, including proliferation and self-renewal, which are also characteristics of glioma cells." (PMID 36003330, 2022). "CRNDE has been reported to promote the proliferation, migration, and invasion of glioma through attenuating miR-384/PIWIL4/STAT3 axis and facilitating EGFR activation to modulate glioma growth." (PMID 36033510, 2022). "Moreover, the EGFR and MUC16 mutations were also significantly enriched in cases within high‐risk group, while mutations in CIC, NOTCH1, ATRX, and CDH12 occurred more frequently in the low‐risk group, these characteristics are consistent with the update WHO CNS5 classification of glioma." (PMID 35985661, 2022). "Overall, our study postulates a disturbance in the EGFR/MUC4/MMP9 signalling axis as a potential novel and rationalized biomarker panel for glioma." (PMID 36400876, 2022). "The epidermal growth factor receptor (EGFR) is a known biomarker of gliomas of high malignancy, and, since 2021, it has been included into the WHO classification of gliomas." (PMID 36615487, 2022). "The EGFR inhibitors osimertinib and afatinib were trialed in three patients with bithalamic gliomas (1 grade II, 2 grade III) exhibiting EGFR exon 20 insertions." (PMID 35978801, 2022). "EGFR, MMP9, and MUC4 expression levels were assessed in FFPE tissue biopsies from 60 glioma patients (20 grade II, 20 grade III, and 20 GBM patients, following the 2016 WHO classification)." (PMID 36400876, 2022). "In glioma, the high expression of HDAC9 can promote proliferation and tumor formation and accelerate the cell cycle in part by potentiating EGFR signaling pathways." (PMID 35545840, 2022). "As a result of both experiments (EGFR and GFAP), we conclude that IgG binding to the EGFR phospho-peptide exists in plasma of glioma patients but not in plasma of healthy donors, and that autoantibodies against EGFR phospho-site S1166 are associated with high-grade glioma." (PMID 35563452, 2022).
glioma (continued). "The overexpression of EGFR will excessively activate EGFR-dependent signal pathways including PI3K/Akt, JAK2/STAT3, and Ras/MAPK in the course of EMT in gliomas." (PMID 36338770, 2022). "In mouse models of glioma, selective inhibition of SRC affected the motility of EGFR-dependent tumor cells." (PMID 35891968, 2022). "In gliomas, high expression of HDAC9 promotes proliferation and tumorigenesis, in part by enhancing the EGFR signaling pathway to accelerate cell cycle." (PMID 36227941, 2022). "In both normal and cancer cells, EGFR stimulates the PI3K/Akt pathway, and EGFR gene amplification in glioma cells results in constitutive PI3K activation." (PMID 35163279, 2022). "This implies EGFR, at least individually, may not be a powerful diagnostic biomarker in glioma." (PMID 36400876, 2022). "NOTCH3 promotes glioma cell invasion and proliferation through activation of cell cycle protein D1 (CCND1) and EGFR gene expression." (PMID 36382054, 2022). "Research showed that PI3K/Akt pathway has a high possibility to be activated in gliomas, with potential mechanisms including PTEN gene change, EGFR gene amplification, and non-coding RNAs." (PMID 36338770, 2022). "Consequently, the expression of circulating miR-155, miR-410, and miR-181a/b and its putative gene-targets PDCD4, WNT5A, MET, and EGFR had a strong inverse relation in high-grade glioma, thereby suggesting that the potential roles of miR-155, miR-410, and miR-181a/b in oncogenesis of glioma tumors." (PMID 35646622, 2022). "Knockdown of HDAC1 resulted in a significant decrease in the expression of glioma master transcription factors SOX2 and OLIG2, stem cell marker NESTIN, and the receptor tyrosine kinase epidermal growth factor receptor (EGFR)." (PMID 34494550, 2021). "Herein the vector expresses a small hairpin RNA-targeting EGFR and wild-type PTEN cDNA in glioma cells." (PMID 33790740, 2021). "PI3K and Akt are downstream effectors of EGFR, while the EGFR-PI3K-Akt pathway is reportedly crucial for glioma progression." (PMID 33407703, 2021). "DYRK1A prevents endocytotic degradation of EGFR through phosphorylation of the EGFR-signaling modulator Sprouty 2 (SPRY2) and DYRK1A inhibition leads to reduced glioma growth." (PMID 34117217, 2021). "The prognostic significance of EGFR and CDKN2A alterations on regulated genes in patients with glioma was determined using the TCGA and the Chinese Glioma Genome Atlas (CGGA) datasets." (PMID 33959491, 2021). "Important signaling pathways altered in gliomas include the growth factor receptor tyrosine kinase (RTK) signaling pathways, partly as a result of PDGF and EGFR overexpression." (PMID 33790740, 2021). "The amplification frequencies of LANCL2 and EGFR in GBM were up to 27.65% (159 of 575 cases) and 44.35% (255 of 575 cases), whereas those in low-grade glioma (LGG) were only 3.91% (20 of 511 cases) and 7.63% (39 of 511 cases), respectively." (PMID 34461927, 2021). "In the gliomas, high expression of DYRK1A correlates with epidermal growth factor receptor (EGFR) expression." (PMID 34117217, 2021). "Known prominent events include TMPRSS2-ERG in PCa, EGFR, CDK4, and MDM2 in glioma, and CCND1 in BrCa." (PMID 34891161, 2021). "EGFR and RAF1 fusions additionally displayed substantial cancer type-specificity, with 65% of 5′ EGFR fusions occurring in gliomas and 69% of 5′ RAF1 fusions occurring in thyroid carcinomas (THCAs)." (PMID 34795215, 2021).
glioma (continued). "Actually, there have been studies indicating the cross talk between EGFR and Wnt/PCP pathway and collaborative contribution to glioma progression." (PMID 34540693, 2021). "Intriguingly, suppressing P2 × 7R with an antagonist or shRNA promotes cell growth through the up-regulation of EGFR, p-EGFR, HIF-1α, and VEGF in glioma cells." (PMID 34149360, 2021). "In the context of EGFR signaling, it has been shown that the EGFR-to-MYC axis utilizes epigenetic mechanisms to silence microRNAs in gliomas." (PMID 34206026, 2021). "MiR-375 suppressed glioma proliferation, migration, and invasion by inhibiting the CTGF-epidermalgrowthfactorreceptor (EGFR) signalling pathway." (PMID 33407703, 2021). "For example, Alqudah MA elucidated that via activation of CCND1 and EGFR, NOTCH3 promotes glioma cell proliferation, migration and invasion." (PMID 33676540, 2021). "There were multiple, cancer type–specific hot spots of junctions located near known oncogenes such as KIT, PDGFRA, EGFR, CDK4, MDM2 (glioma), TMPRSS2, ERG (PCa), FGFR1, and CCDN1 (BrCa)." (PMID 34891161, 2021). "DH1, TERT, EGFR, PTEN, ATRX and other key factors are expressed in gliomas as in human GBM, and EGFR is upregulated in tree shrew GBM." (PMID 33768009, 2021). "The results showed that there was a positive correlation between NUP37 and most known biomarkers of glioma such as ATRX, EGFR MGMT, CDK4, and so on." (PMID 34264013, 2021). "Our investigation on 751 gliomas showed genetic changes of PTEN in 76%, PIK3AP1 and CHUK in 75%, and EGFR in 74% of the total samples." (PMID 34209611, 2021). "Data on CNA show that genes AKT2, AKT3, CHUK, EGFR, PIK3AP1, and PTEN show an increase in copy number alterations with the increased glioma grade." (PMID 34209611, 2021). "Lapatinib is an antineoplastic, clinically approved PS that acts as an epidermal growth factor receptor (EGFR) inhibitor; however, it has poor penetration into glioma cells." (PMID 34575424, 2021). "Apart from ependymomas, radiomics has also shown potential in creating phenotypic signatures of glioma genotypes such as isocitrate dehydrogenase (IDH), epidermal growth factor receptor (EGFR), and O6-methylguanine-DNA-methyl-transferase (MGMT)." (PMID 34367044, 2021). "LncRNA LPP-AS2 plays an important role in regulating the miR-7-5p/EGFR/PI3K/AKT/c-MYC feedback loop, which is correlated with glioma tumorigenesis." (PMID 34178684, 2021). "For example, EGFR and STAT3 were both highly expressed in gliomas and negatively correlated with the overall survival of gliomas." (PMID 34264013, 2021). "As compound 10 was designated as the most potent and selective anti-glioma agent according to MTT results, its further apoptotic and EGFR inhibitory effects were also investigated to provide mechanistic insight." (PMID 34681605, 2021). "Among the 1,004 glioma patients in the MSKCC datasets, 27% patients had EGFR alteration and 33% patients had CDKN2A deletion." (PMID 33959491, 2021). "Few studies have reported different therapeutic targets, such as mTOR, EGFR, and VEGFR, for the treatment of glioma." (PMID 34838021, 2021). "In the present study, we tried to analyze the prognostic significance of epidermal growth factor receptor (EGFR) amplification and CDKN2A alteration on regulated genes in patients with glioma." (PMID 33959491, 2021). "The EGFR or PTEN alteration induces continuous stimulation of the PI3K/Akt/mTOR pathway and increases activated AKT levels in glioma cells, thereby leading to tumorigenesis and resistance to cancer therapy." (PMID 34199460, 2021). "We first evaluated the inhibitory effects of AZD3759 on the proliferation of glioma cells and the evaluated of the regulatory effects of AZD3759 on the EGFR and JAK pathways in glioma cells." (PMID 34635007, 2021).
glioma (continued). "EGFR and ERBB2 were notably downregulated in IDH mutant gliomas, while ERBB3 and ERBB4 were upregulated, which was associated with a poor prognosis." (PMID 33892666, 2021). "This was further confirmed by the maintenance of patient-specific EGFR amplification and phosphorylated RTK signals by glioma organoids, as well as the spontaneous formation of Glioma Organoids microtubules, and microstructure features were also found in situ." (PMID 34635112, 2021). "We next repeated this process for each grade of glioma and found that these enhancers regulated a number of cancer-related genes, such as ARID1B 39, EGFR, MDM2 40, PRGFRA, and MYC." (PMID 33537074, 2021). "The human RTK family has 58 known members; these are further classified into 20 multi-member subfamilies including EGFR, VEGFR, PDGFR, FGFR, and MET, which are the most commonly studied RTKs in glioma initiation and progression." (PMID 34806012, 2021). "In glioma samples with high LYN expression, oncogenic driver genes such as EGFR (7p11.2) and CDK4 (12q14.1) were frequently amplified, while tumor suppressor gene PTEN (10q23.31) and CDKN2A (9p21.3) were frequently deleted." (PMID 35186945, 2021). "In particular, EGFR, in turn, hyperactivates the phosphatidylinositol 3′ kinase (PI3K)/AKT signaling pathway, which is involved in the regulation of glioma cell survival, proliferation and motility." (PMID 34201962, 2021). "As examples for EGFR-overexpressing cancer cells, we have selected the bladder cancer cell line EJ28-Luc and the glioma cell line LN1815." (PMID 33737524, 2021). "The role of ErbB [epidermal growth factor receptor (EGFR)] in GBM and glioma has also been extensively studied." (PMID 34482818, 2021). "GALNT2 knockdown and overexpression in glioma cells demonstrated that GALNT2 was related to cell proliferation, migration and invasion through the EGFR/PI3K/AKT/mTOR signaling pathway." (PMID 34069424, 2021). "Since the co-amplification of LANCL2 and EGFR was found in GBM in 2002, studies of LANCL2 are barely reported in glioma till now." (PMID 34461927, 2021). "The clinical characteristics of glioma patients from TCGA consisting of primary therapy outcome, WHO grade, histological type, IDH status, gender, 1p/19q codeletion, age, race, EGFR status, and PIK3CA status were collected." (PMID 34222249, 2021). "The Kruskal–Wallis test confirmed a significant difference in methylation of all examined genes between glioma types (p < 0.001 for AKT1, AKT3, CHUK, GSK3β, EGFR, PTEN, PIK3AP1; p = 0.032 for AKT2)." (PMID 34209611, 2021). "The expression level of EGFR mRNA was notably negatively correlated with the infiltration level of DCs (r = − 0.09997, p = 0.0088) and CD4+ T cells (r = − 0.1143, p = 0.0027) in glioma tissue." (PMID 33892666, 2021). "For EGFR-KDD, glioma has the highest frequency (2.4%, 222/9381), followed by NSCLC (1.4%, 70/48,699) and GI (0.3%, 40/11,822)." (PMID 33654076, 2021). "Notably, the EGFR and IL13Ra2 glioma markers were clearly detected after neuronal conversion at 20 days after Neurog2 infection 42–44, suggesting that the newly converted neurons may still have retained characteristics of GBM cells, at least for the early time period after conversion." (PMID 33755378, 2021). "Recently, their finding has been expanded with a role for the EGFR-Ras-MAPK signaling pathway by upregulation of COP9 signalosome complex subunit six (CSN6) and subsequent stabilization of PD-L1 in gliomas." (PMID 33718186, 2021). "C-E-Cad binds to the EGFR CR2 domain and activates EGFR with a unique 14-amino acid carboxyl terminus, thereby maintaining the tumorigenicity of glioma stem cells." (PMID 34526007, 2021).
glioma (continued). "After activation of EGFR, Phosphatidylinositol 3-kinase (PI3K)/Akt/rapamycin-sensitive (PI3K/Akt/mTOR) signal pathway plays role in the genesis and development of glioma." (PMID 34356101, 2021). "EGFRs are highly expressed in tumor tissues of patients with glioma, and 20%–30% patients carry the EGFR VIII mutant gene, which is the mutant tumor gene commonly observed in glioma." (PMID 34635007, 2021). "LRIG2 belongs to the leucine-rich repeats and immunoglobulin-like domains family and regulates epidermal growth factor receptor (EGFR) signaling pathway, and downregulation of LRIG2 suppressed angiogenesis in glioma." (PMID 33762949, 2021). "Another study reported that LPP-AS2 regulates EGFR expression by sponging Mir-7-5p as a ceRNA and combination of the promoter region of LPP-AS2 with c-MYC contributes to the development of glioma." (PMID 34425868, 2021). "In 2016, the revised classification of central nervous system tumors was constructed based on genetic and epigenetic alterations, including IDH 1/2, MGMT methylation, 1p/19q codeletion, and EGFR." (PMID 34568031, 2021). "Expression of LPP-AS2, epidermal growth factor receptor (EGFR) and miR-7-5p in glioma tissues and cell lines was detected by real-time quantitative PCR (RT-qPCR), and the functions of lncRNA LPP-AS2 in glioma were assessed by in vivo and in vitro assays." (PMID 32962742, 2020). "The EGFR and MET activation and the downstream of EGFR and MET signaling pathways, such as p-AKT, p-p38, p-STAT3 and p-p65 in TMZ-resistant glioma cells, were also mitigated by BIP-MPC-NP, as expected." (PMID 32001707, 2020). "In glioma cells, CSN6 stabilizes epidermal growth factor receptor (EGFR) by enhancing the self-ubiquitination of E3 ubiquitin ligase CHIP, thereby promoting glioma cells proliferation, migration and invasion." (PMID 33162808, 2020). "In the glioma pathway (hsa05214), included in CDK4 (Cyclin Dependent Kinase 4), PRKCG (Protein Kinase C Gamma) and EGFR." (PMID 32696617, 2020). "Studies predicting glioma genes based on radiomics mainly focused on the IDH, 1p/19q, MGMT, ATRX, and EGFR genes, which all agreed that radiomics was an excellent noninvasive method for predicting the genetic status of glioma." (PMID 32509858, 2020). "Oncogenic drivers including PIK3C2B, EGFR, and CDK4 are amplified in gliomas with low TOX expression." (PMID 32762688, 2020). "Indeed, genetic alterations in EGFR and SETD2 frequently co-occur in glioma and TCGA pan-cancer cohort, supporting the notion that co-occurring EGFR and SETD2 alterations cooperate to promote tumor progression, and that SETD2-mutant cancer may evolve a dependency on EGFR signaling." (PMID 32824422, 2020). "The present study indicated that the expression level of the EGFR, ERK-1,2 and AKT-1,2 in glioma cell lines is medium and can induce cell growth in these cells." (PMID 33369441, 2020). "Repression of cZNF292 suppressed glioma tube formation via the Wnt/β-catenin pathway and related genes such as EGFR, VEGF-A, and the VEGF-A receptor VEGFR-1/2 in human glioma U87MG and U251 cells." (PMID 32061256, 2020). "Taking advantage of the conservation of genes of the EGFR and PI3K pathways, preclinical glioma models have been made in Drosophila melanogaster – a powerful in-vivo genetic model system." (PMID 32457905, 2020). "Here, the authors develop a dual functionalized brain targeting nano-inhibitor to simultaneously target EGFR and MET pathways, and show this can overcome temozolomide resistance in glioma." (PMID 32001707, 2020). "Acute human glioma cell stimulation with EGF evokes intracellular Ca2+ responses as oscillations, which are blocked by EGFR inhibitors." (PMID 32841278, 2020).